CDK1 (cyclin dependent kinase 1)
Diseases named in the same sentence as CDK1 in open-access papers (continued):
Sharing a sentence is not in itself a finding about the gene and the disease.
cancer (continued). "Targeting cyclin-dependent kinase 1 (CDK1) in cancer: molecular docking and dynamic simulations of potential CDK1 inhibitors." (PMID 37675062, 2023). "Altogether, these observations suggest that while the CDK1 protein level is high in most of the cancer tissues, its activity, as revealed by its phosphorylation status on regulatory sites, seems to be suppressed." (PMID 37898722, 2023). "Several anti-tumor agents, such as dinaciclib, apigenin, LX1570, and matrine, were found to induce cellular stress via CDK1 inhibition in cancer cells." (PMID 37569750, 2023). "Kaempferol treatment showed a role in the G2/M cell cycle arrest, and the expression of cyclin B and CDK1 decreased in kaempferol-treated cancer cells." (PMID 37239974, 2023). "The upstream modulators of CDK1 in cancer include various molecular factors that can positively or negatively influence CDK1 activation, amplification, transcription, and expression." (PMID 37311884, 2023). "In this review, we focused on the role the CDK1 in cancer and examined the potential application of targeting CDK1 for cancer treatment." (PMID 37311884, 2023). "Among them, we selected Il-21, Cxcl13, Cdk6, Cdk1, and Cxcr7, all cytokine, cell cycle, or cancer-related genes." (PMID 37304286, 2023). "There is however, a well-known inhibitor, RO3306, that is specific to CDK1 and has shown inhibition of the kinase in many cancer models including PCa." (PMID 36937454, 2023). "Here we exploited pan-cancer (phospho)proteomic dataset stored in different databases to clarify the correlation between the phosphorylation of specific regulatory sites of CDK1 and consequently its activation with tumorigenesis." (PMID 37898722, 2023). "The inhibition of CDK1 expression by small inhibitors, or CDK1 knockdown, reduces cell viability, induces apoptosis, and impairs cell migration in multiple types of cancer cell lines and xenograft mouse models." (PMID 37569750, 2023). "Secondly, and importantly for cancer therapy, the upregulation of Cdk1 activity by Wee1 inhibition can force cancer cells to enter mitosis with under-replicated or unrepaired chromosomes leading to mitotic catastrophe and chromosome fragmentation." (PMID 38020882, 2023). "The ATMi and Chk1i combination synergistically promotes CDK1 activation, resulting in the induction of apoptosis with enhanced cell cycle progression in cancer cells." (PMID 36765693, 2023). "Collectively, this evidence reveals the complex interplay between CDK1 phosphorylation, activation and crucial cancer-related processes such as apoptosis, cell cycle regulation, drug resistance, and invasive potential." (PMID 37898722, 2023). "The core effect of CR on ten cancer cell lines is to induce G2/M arrest by inhibiting the PLK1/CDK1/Cyclin B axis." (PMID 37007025, 2023). "The reliance of many cancer cells on Cdk1 for sustainable proliferation increases the chance of cell death when ectopic Cdk1 activity is promoted." (PMID 38020882, 2023). "Given that increasing the activity of CDK1 has been found to enhance the ability of tumor cells to invade and migrate, as shown in other cancer types, we investigated the effect of RO-3306 on adhesion and invasion in OC cell lines and tumors." (PMID 37569750, 2023). "In accordance with their crucial role in the cell cycle and DNA repair and their overexpression in cancer cells, CDK-1 and PARP-1 were demonstrated to be key targets in BC progression." (PMID 37762072, 2023). "IMMT levels positively correlated with biomarkers linked to cancer proliferation (KI67, PCNA, and MCM2) and with key regulators of the cell cycle (CDK4, CDK2 and CDK1)." (PMID 36899366, 2023). "CDK1 inhibition stimulated G2/M arrest and apoptosis in multiple cancer cell lines and decreased tumor growth in vivo in the mouse xenograft model." (PMID 37529110, 2023). "Then, we used a series of in vitro experiments to demonstrate that CR can dramatically inhibit the growth of ten cancer cell lines by blocking the PLK1/CDK1/Cyclin B axis." (PMID 37007025, 2023).
cancer (continued). "Keeping in mind that these profiles represent a snapshot of the underlying cancer process, we observed that the expression of CDK1 and CDK4 increased significantly with the tumor’s pathologic stage in KICH (CDK1, p = 1.37 × 10−5 and CDK4, p = 6.39 × 10−3)." (PMID 37047552, 2023). "In recent years, several small molecules with anticancer activity that target CDK1 and other CDKs have been identified in preclinical and clinical studies focusing on multiple cancer types." (PMID 37311884, 2023). "SCL/TAL1 interrupting locus (STIL) promotes proliferation, invasion, and cancer progression by regulating the expression of CDK1, CCNB2, CDC20, CCNA2, BUB1, and AURKB." (PMID 36661515, 2023). "Collectively, CDK1 is clearly involved in multiple cancer-related pathways, suggesting the significance of CDK1 in various cancer processes." (PMID 37311884, 2023). "This indicated that treatment with 9-oxo-ODAs increased cancer cell apoptosis and decreased CDK1 protein expression ex vivo." (PMID 37932321, 2023). "It appears that ZBSO inhibits cancer through the downregulation of PCNA protein and pathways associated with CDC25A/CyclinB1/CDK1." (PMID 37081962, 2023). "RO-3306157–159 and CGP-74514A160,161 are specific CDK1 inhibitors that effectively suppress the growth of cancer cells and patient derived xenografts (PDX)." (PMID 37311884, 2023). "Increasing evidence suggests that CDK1 phosphorylates downstream substrates that play critical roles in cancer progression signaling pathways." (PMID 37311884, 2023). "Together, our results uncover a previously unrecognized function of CDK1 to promote tumor progression through destabilizing pVHL in cancer harboring wild-type VHL." (PMID 36813923, 2023). "More importantly, CDK1 is a well-known cancer-promoting factor in NSCLC, implying CDK1 as a potential downstream of NLE1." (PMID 36818671, 2022). "CDK1 inhibition induces cell cycle arrest in the G2-M phase and apoptosis and targeting CDK1 has showed promising results for cancer treatment in different preclinical models." (PMID 36555165, 2022). "6-O-angeloylplenolin, coronopilin, pulchelloid A, and hymenoratin, 5/7-bicyclic pseudoguaianolide SLs also induce high p-Cdk1 and/or Cdk1 and cyclin B1 expression in certain cancer cell types." (PMID 35651747, 2022). "The activated CDKs are necessary for cancer cell proliferation, and CDK1 is essential for the phase transition of G1/S and G2/M." (PMID 35236335, 2022). "We demonstrated that HRASV12-induced cyclin-dependent kinase 1 (CDK1) activity and subsequent enhancement of protein O-GlcNAcylation were required for SOX2 induction and CSC generation in these fibroblasts and cancer cell lines containing RAS mutations." (PMID 35190631, 2022). "We compared the expression levels of the CDK1 gene in the TCGA and GTEx database integrated datasets, considering the limited paracancerous normal tissue of some cancer species in the TCGA database." (PMID 36090896, 2022). "DNA methylation directly affects cancer development, and hence, we investigated the DNA methylation levels of CDK1 in different tumors using the TCGA dataset in the UCLAN database." (PMID 36090896, 2022). "Taken together, these findings provide insights into the application of CDK1 as a prognostic marker for pan-cancer in the context of immuno-oncology, thus contributing to the potential development of research on CDK1 gene-targeted therapy." (PMID 36090896, 2022). "CDK1 was also positively correlated with tumor mutational burden (TMB) and microsatellite instability (MSI) in certain cancer types, linking its expression to the assessment of possible treatment response." (PMID 36090896, 2022). "In BETi-resistant cancer cells, CDK1 upregulation and BRD4 hyperphosphorylation were observed, including triple-negative breast cancer (TNBC)." (PMID 35402244, 2022).
cancer (continued). "HMGB1 showed a positive association with CDK1 (R = 0.51), SSRP1 (R = 0.57), H2AFV (R = 0.53), and HMGB2 (R = 0.57) genes in several cancer types and these data were visualized as a heatmap." (PMID 36230798, 2022). "Future studies are required to clarify the role of CDK1 in cancer cell proliferation and invasion and to design specific CDK1 inhibitors to improve anticancer efficacy and reduce side effects." (PMID 35681641, 2022). "Our study reveals a significant positive correlation between CDK1 and RNA methylation regulatory proteins at the pan-cancer level of expression." (PMID 36090896, 2022). "In this study, we used independent datasets from TCGA, Kaplan-Meier plotter, and PrognoScan to determine the relationship between CDK1 expression levels and pan-cancer prognosis." (PMID 36090896, 2022). "As an important locus of signaling pathways, the CDK1 gene is essential for tumor initiation and progression in different types of cancer, promoting the progression of malignancy through different signaling pathways." (PMID 36090896, 2022). "Clinically, CDK1-mediated phosphorylation of human telomerase reverse transcriptase (hTERT) at T249 is closely related to aggressive and advanced cancers." (PMID 35681641, 2022). "Analysis of H hallmark gene sets and C6 oncogenic signature gene sets in the molecular signatures database (MSigDB) demonstrated that coherent expression and cellular pathways were often dysregulated in cancer cells based on the levels of CDK1 expression." (PMID 35681641, 2022). "Paired analysis showed that the expression level of CDK1 in most cancer tissues was higher than that in normal tissues in LUAD." (PMID 35406786, 2022). "Considering a reduction of cyclin B1 and CDK1 by apigenin has been reported in other cancer cell lines, it is possible that the impeding effect imposed on G2-M transition by apigenin is a general mode of action in a broad range of cancer cells." (PMID 35670862, 2022). "Meanwhile, this high expression status of CDK1 gene can significantly reduce survival time of tumor patients as revealed at the pan-cancer level." (PMID 36090896, 2022). "A large number of studies have shown that CDK1 is closely related to the occurrence and development of malignant tumors." (PMID 36818671, 2022). "AURKA overexpression constitutively activates CDK1 and abolishes the G2/M DNA damage checkpoint in cancer cells." (PMID 35699421, 2022). "Cyclin-dependent kinase 1 (CDK1) plays an important role in cancer development, progression, and the overall process of tumorigenesis." (PMID 36090896, 2022). "CDK1 is known to play an important role in cervical carcinogenesis and mediates the progression of cancer cells through S and G/M phase via binding to cyclin A and cyclin B protein, respectively." (PMID 36088372, 2022). "WEE1, which can inhibit the function of CDK1-cyclinB complex, is a potential target for cancer therapy." (PMID 35928440, 2022). "Upon mitotic entry—or potentially in certain cancers—Cdk1 activity increases, leading to Sam68 phosphorylation at T33 and T317." (PMID 36537190, 2022). "Given the complexity of tumorigenesis, it is extremely important to analyze the CDK1 gene for pan-cancer expression and to assess its relationship with clinical prognosis and its relevance to the underlying molecular mechanisms." (PMID 36090896, 2022). "As the next step, KNTC1 knockdown caused some cancer-associated factors P-Akt, CCND1, c-Myc, CDK1 and PIK3CA depletion." (PMID 35933405, 2022). "The results of the database demonstrated that CDK1 was moderate to strong nuclear staining in majority cancers." (PMID 35601741, 2022). "An integrative human pan-cancer analysis showed that dysregulation of CDK1 was identified in more than 20 human tumors and was significantly correlated with the development, progression, and microenvironment of tumor cells." (PMID 36333684, 2022).
cancer (continued). "By in silico analysis of the ACC dataset in the cancer genome atlas (TCGA), we determined that high expression levels of cyclin-dependent kinase-1 (CDK1) were significantly related to the adverse clinical outcomes of ACC." (PMID 36184616, 2022). "For example, dinaciclib, a potent CDK1/2/5/9 inhibitor, has been shown to induce apoptosis of cancer cells, and its combination with checkpoint immunotherapy resulted in an enhanced anti-tumor response." (PMID 35884422, 2022). "Our pan-cancer analysis showed a significant positive correlation with expression between the CDK1 gene and three classes (m1A, m5C, m6A) of RNA methylation regulatory proteins." (PMID 36090896, 2022). "The present study was designed to use a pan-cancer analysis to understand the role of CDK1 in human tumor development, progression, and clinical outcomes, as well as potential signaling pathways." (PMID 35681641, 2022). "Akt phosphorylates p21 at Ser 146 increasing it protein stability for action on the inhibition of CDK1 activity and enhances cancer cell survival." (PMID 34064109, 2021). "Dysregulation of CDK1 induced not only accelerated tumor growth but also sustained or spontaneous proliferation of cancer cells and even metastasis." (PMID 34895070, 2021). "As cancer cells often display enhanced CDK1 activity, CDK1 is frequently proposed as a tumor specific marker." (PMID 34356619, 2021). "In another study, miR-186-3p reduced the expression of cyclin-dependent kinase 1 (CDK1) and influenced the cell cycle regulation of cancer cells." (PMID 34253194, 2021). "Direct overexpression of CDK1 or of its activating subunit cyclin B (CNNB1/2) are obvious additional possibilities to achieve higher CDK1 activity in cancer." (PMID 33168930, 2021). "Overexpression of CDK1, MCM2, E2F2, PLK1, CCNB1/2, BUB1, BUB1B, CDC25 has been associated with aberrant proliferation in many cancer types including HCC." (PMID 33499054, 2021). "The hub protein cyclin-dependent kinase 1 (CDK1) plays a key role in regulating cell cycle progression, and is a potent therapeutic target for inhibitors in the treatment of cancer." (PMID 33462336, 2021). "Abnormal mitosis induced by CCNB1/CDK1 complex is an enormous element of cancer development or progression." (PMID 34858850, 2021). "Modulation of mitochondrial oxidative metabolism fuel to produce ATP required for cancer cell survival was related to CDK1–cyclin B1 activity." (PMID 34064109, 2021). "Cluster 4 showed high expression of cell cycle‐related genes for markers such as PCNA, MCM5, MKI67, STMN1, and CDK1, probably owing to the immune response to cancer neo‐epitopes." (PMID 33513276, 2021). "Coincidentally, it has been reported that Oxymatrine can simultaneously inhibit both EGFR/MAPK3/1 and EGFR/CDK1 pathways to arrest the cycle in multiple cancer cell lines." (PMID 34809653, 2021). "Given the fact that unleashed CDK1 is central to the induction of CIN, one has to consider various routes that can lead to increased CDK1 activity in cancer cells." (PMID 33168930, 2021). "Liver hepatocellular carcinoma patients who were with advanced cancer stages inclined to have the higher mRNA expression levels of CDK1, HMMR, PTTG1, and TTK." (PMID 34187556, 2021). "Secondly, CDK1 overexpression leads to the stimulation of a range of proteins that induce stem cell properties, which can contribute to the development of cancer stem cells (CSCs)." (PMID 34503199, 2021). "The activity of CDK1 is often enhanced in cancer cells, it therefore has been considered as an appealing specific anti-cancer target." (PMID 34899687, 2021). "CDK1, a cyclin-dependent kinase, plays an important part in regulating cell cycle progression and reportedly increases cellular proliferation in various cancers if dysregulated." (PMID 33879165, 2021). "Vice versa, partial inhibition of CDK1 activity in chromosomally unstable cancer cells corrects abnormal microtubule behavior and suppresses W-CIN." (PMID 33168930, 2021).
cancer (continued). "Secondly, CDK1 inhibition can sensitize specific cancer types that would be unsensitive by a specific form of chemotherapy alone, extending the therapeutic spectrum of these drugs." (PMID 34503199, 2021). "mRNA levels of TTK, NEK2, and CDK1 increased during the development of cancer from stage 1 to stage 4." (PMID 34072728, 2021). "Various studies described the effect of CDK1/cyclin B complex activity inhibition on cancer cell cycle proliferation." (PMID 34503199, 2021). "The result indicated that there was obvious difference in mRNA expression of CDK1 between cancer tissues and normal esophageal tissues, and the expression of CDK1 was obviously increased in ESCC tissues (5.261 ± 0.703 vs. 2.229 ± 1.161, P < 0.0001)." (PMID 34586751, 2021). "Deregulated CDK1 and cyclin B activities were negatively correlated in many cancer types including breast, lung and colorectal tumors." (PMID 33805800, 2021). "In this sense, we have shown that CDK1 is essential for the toxic effects of USP7 inhibitors in cancer cells." (PMID 34445496, 2021). "It is postulated that preventing the up-regulation of the CDK1 axis improves the sensitivity of cancer cells to chemotherapeutic agents, increasing their effectiveness." (PMID 34281228, 2021). "Reduction of CDK1 activity can both sensitise cancer cells to treatment and enlarge the therapeutic spectrum of existing therapies." (PMID 34503199, 2021). "The exact mechanism linking between PI3K–Akt signaling and CDK1–cyclin B1 to dictate ER–mitochondria metabolic function in cancer cell survival remains an open issue." (PMID 34064109, 2021). "Here, the high risk HCC patient group has been found to be characterized by the upregulation of several effectors that play a role within the CDK1 network and that are usually upregulated in cancer." (PMID 33499054, 2021). "Mechanistic studies demonstrate that esomeprazole arrests cancer cells in the G1 phase of the cell cycle through upregulation of p21 protein and inhibition of cyclin-dependent kinases (Cdks) type 1 (Cdk1) and type 2 (Cdk2)." (PMID 34262645, 2021). "These cancer cells expressing CDK1 were stimulated to apoptosis upon siRNA knockdown or the knockdown of small molecules, such as the CDK1 inhibitor RO-3306 or the CDK1,2,5,9 inhibitor dinaciclib." (PMID 34946546, 2021). "OXA also inhibited homologous recombination by CDK1 activity and importantly made cancers with normal BRCA1 function sensitive to PARP inhibition." (PMID 34497808, 2021). "The mutations of CDK-1 and CDK-4 were carried out using the COSMIC database for CRC coupled with the cBioPortal database for hotspot mutation in human cancers." (PMID 33732631, 2021). "In fact, overexpression of CDK1 or of CNNB1/2 is frequently found in various human cancers and correlates with poor prognosis." (PMID 33168930, 2021). "CDK1 is a key cell cycle regulator and its inhibition in the eradication of cancer has been extensively studied." (PMID 34093198, 2021). "Of note, AT7519 likewise reduced phosphorylation of RNA polymerase II via CDK1/9 and affected expression levels of the oncoprotein N-Myc, making this compound a candidate for treatment of N-Myc-driven cancers." (PMID 33161487, 2021). "CDK1 is considered a synthetic target for KRAS-mutated tumors and has been identified as a prognostic marker in numerous types of cancer." (PMID 34917126, 2021). "These lines of evidence provided the basis for NSC77201 directly regulating activities of TTK, NEK2, and CDK1, which result in antitumor effects in multiple cancer types." (PMID 34072728, 2021). "This also explains studies demonstrating that CDK1 inhibition reduces gemcitabine- and 5-FU resistance in multiple different cancer types." (PMID 34503199, 2021).